RHOA (ras homolog family member A)
Diseases named in the same sentence as RHOA in open-access papers (continued):
Sharing a sentence is not in itself a finding about the gene and the disease.
diabetes (continued). "In the present study, we tested the hypothesis that down-regulation of miRNA-133a due to oxidative stress mediates up-regulation of RhoA/Rho kinase pathway leading to hypercontractility and delayed gastric emptying in diabetes." (PMID 28678840, 2017). "Changes in the miRNA-133a levels and miR-133a-driven RhoA expression in diabetes could be due to increase in oxidative stress." (PMID 28678840, 2017). "We tested the hypothesis that the upregulation of RhoA/Rho kinase pathway in diabetes is due to decrease in miR-133a expression." (PMID 28678840, 2017). "RhoA/ROCK signaling is also involved in diabetes-induced vascular dysfunction." (PMID 27724862, 2016). "Data from one study suggests that diabetes impairs cardiac function through upregulation of RhoA." (PMID 23596480, 2013). "Previous studies suggested that the RhoA/ROCK pathway may contribute to vascular complications in diabetes." (PMID 22694757, 2012). "Importantly, from a diabetes perspective, studies have demonstrated a significant correlation between increased RhoA activity and impaired vascular function in experimental models of T1D and T2D." (PMID 22013533, 2012). "Previous reports documented that oxidative stress and diabetes activate RhoA." (PMID 21052489, 2010). "Our data suggest that in both Type 1 and Type 2 models of diabetes activation of the rhoA/rho kinase pathway may be increased in arteries from diabetic males despite no change in protein expression." (PMID 20368772, 2010). "Of note, our recent studies demonstrated that a parallel mechanism by which activation of RhoA/Rock and subsequent upregulation of arginase expression and activity can contribute to decreases in NO formation and endothelial dysfunction in experimental models of diabetes." (PMID 21052489, 2010). "In addition to rhoA and rho kinase contributing to alterations in contractile dysfunction in diabetes, numerous studies have identified other signaling pathways including protein kinase C contributing to changes in calcium sensitization of contractile proteins in vascular smooth muscle." (PMID 20368772, 2010). "For example, hyperglycemia-induced mitochondrial fission and dysfunction in endothelial cells is mediated by activating the RhoA/ROCK1/Drp1 signaling pathway, thus contributing to vascular complications of diabetes." (PMID 35769086, 2022). "On the other hand, the RhoA/ROCK/dynamin-related protein-1 (Drp1) and F-actin/mitochondrial fission/ROS/apoptosis pathway has been reported in various diseases including diabetes, hypertension and Parkinson’s disease." (PMID 35769086, 2022). "Due to the communication between GENs and mesangial cells in diabetes, ET-1 binding to ETAR in mesangial cell promoted RhoA/ROCK pathway, thus to accelerate mesangial cell proliferation and ECM accumulation." (PMID 30926764, 2019). "In conclusion, the present study demonstrates that BSHX prescription effectively improves diabetes-induced cognitive impairment and cerebral microangiopathy through inhibition of AGEs-RAGE induced expression of RhoA/ROCK/moesin signaling pathway." (PMID 29867568, 2018). "An importance of oxidative stress in mediating these changes in diabetes was demonstrated using NAC which is capable of reversing the effect of diabetes on the miR-133a and RhoA expression, Rho kinase activity, muscle contraction and gastric emptying." (PMID 28678840, 2017). "Berberine ameliorates the microvascular complications of diabetes, the renoprotective and anti-oxidative stress effect of BBR by inhibiting the activation of RHOA/ROCK signaling." (PMID 27846294, 2016). "Numerous studies have found increased expression and/or activity of RhoA and ROCK in cardiovascular, renal and retinal tissues in animal models of diabetes, while inhibition of ROCK has been found to improve their function." (PMID 24466133, 2014). "It remains to be determined if RhoA upregulation drives ROCK activation and localised coronary constrictions in early diabetes." (PMID 24059472, 2013).
diabetes (continued). "The RhoA/Rho-kinase system is up-regulated in the cavernosal tissue of aged and spontaneously hypertensive (SHR) rats and rats with experimentally-induced diabetes." (PMID 22444253, 2012). "Further analysis revealed that SCEVs were able to reverse the diabetes-induced reduction in several essential miRNAs, such as miR-21, -27a, and -146a, along with the modulation of a diabetes-induced elevation in semaphorin 6A (SEMA6A), RhoA, PTEN, and nuclear factor-kappa B (NF-kB)." (PMID 38139147, 2023). "Prominent genes were RHOA, AKT1, RAC1, MDM2, CDKN1A, and VEGFA, which play important roles in TGF-beta and mTOR signaling (KEGG database), signaling by Wnt and by NOTCH (Reactome database), and in complications in diabetes mellitus (DisGeNET database)." (PMID 35742976, 2022). "RhoA/ROCK-dependent signaling pathways are critically involved in pathological conditions, including pulmonary hypertension, heart attack, stroke, Alzheimer’s disease, glaucoma, diabetes and hypertensive nephropathy." (PMID 36077498, 2022). "In a clinical study of healthy, pre-diabetes, diabetes, and diabetic patients with CVD (DM-CVD) subjects (n = 10-11 per group), DM-CVD neutrophils exhibited a distinct impedance signature and pro-inflammatory transcriptomic profile marked by cytoskeletal dysregulation and altered RhoA signaling." (PMID 41313750, 2025). "In summary, PFN-1 may serve as a novel regulator that mediates the effects of AGEs-activated RhoA/ROCK signaling pathway on the redistribution of actin cytoskeleton, and inhibition of PFN-1 expression can protect against cardiomyocytes injury and cardiac dysfunction in diabetes." (PMID 29238726, 2017).
glioblastoma (53 papers, 2010 to 2025). The most malignant astrocytic tumor (WHO grade IV). "In glioblastoma, the increased activity of Rac1, Cdc42, RhoA, and RhoG is associated with the invasiveness of tumor cells." (PMID 35053605, 2022). "The transmembrane protein ODZ1 has been associated with the invasive capacity of glioblastoma (GBM) cells through upregulation of RhoA/ROCK signaling, but the mechanisms triggering the ODZ1 pathway remain elusive." (PMID 31649891, 2019). "An increase of the RhoA activity in glioblastoma cells has been associated with decreased motility and invasiveness and formation of stress fibres and focal adhesions." (PMID 31075964, 2019). "HHT treatment of GBM can inactivate STAT3 signaling by inhibiting PDGFRα phosphorylation and PDGFRα/Ras homolog family member A (RhoA)/Rho-associated coiled-coil-containing protein kinase (ROCK) axis to reduce glioblastoma cell proliferation, cytoskeletal remodeling, and migration." (PMID 39949739, 2025). "Galectin-1, for instance, enhances glioblastoma cell migration via re-organisation of the actin cytoskeleton and upregulation of small GTPase RhoA expression." (PMID 41516291, 2025). "Resveratrol suppresses the migration and invasion of human glioblastoma cells through the activation of the RhoA/ROCK signaling pathway." (PMID 41369326, 2025). "For instance, a recent study identified a Syx-RhoA-Dia1 signaling axis as a DNA damage regulator and therapy resistance in glioblastoma." (PMID 38002496, 2023). "RHOA, also referred to as Ras homolog family member A, is a member of the Rho family of small GTPases and a key regulator of the invasion and migration of glioblastoma cells." (PMID 37298284, 2023). "This drug reduced vasculogenic mimicry process in glioblastoma cells through inhibition the Src/p120-catenin pathway and inhibition of RhoA-GTPase activity." (PMID 36551529, 2022). "Although a potential role for RhoA, which has been shown to regulate glioblastoma radioresistance via survivin, and ROCK2 in radiation resistance has been suggested, their collective mechanism remains poorly understood." (PMID 35277915, 2022). "In glioblastoma cells, paeoniflorin treatment can suppress tumor cell migration and invasion and actin cytoskeleton rearrangement by inhibiting c-Met-mediated RhoA/ROCK signaling and EMT, deactivating STAT3 signaling, or increasing miR-16 expression." (PMID 36046834, 2022). "Resveratrol possesses a potent effect in inhibiting the invasion and migration capability of glioblastoma cells by activating the RhoA/ROCK pathway." (PMID 32075265, 2020). "In this regard, resveratrol was found to suppress glioblastoma cell migration and invasion by increased activation of the RhoA/ROCK pathway." (PMID 32089990, 2020). "RhoA is a well-established Rho GTPase that plays an important role in cell motility and invasion of glioblastoma and other tumor types." (PMID 32089990, 2020). "Glioblastoma cells with increased RhoA activity are characterized by impaired cell migration due to the induction of profound morphological changes, including actin reorganization into stress fibers and the induction of focal adhesions." (PMID 33327966, 2020). "The Rho family of small GTPases, which includes Rac1, Cdc42, and RhoA, is an important family whose members are key regulators of the invasion and migration of glioblastoma cells." (PMID 32089990, 2020). "Overexpression of PDZ-Rho GEF in TROY-expressing glioblastoma cells mediates RhoA and RhoC activation downstream of the TROY receptor." (PMID 32089990, 2020). "Our study introduces a novel RhoA-driven mechanism utilized by glioblastoma cells to invade the healthy brain parenchyma along myelinated nerve fibers: glioblastoma cells interact with the myelin protein Nogo-A via the S1PR2 receptor." (PMID 31062076, 2019). "We showed that glioblastoma cells with high p-AKT1/ENTPD5 levels produced SPARC in response to acute RhoA activation." (PMID 31062076, 2019).
glioblastoma (continued). "In our present study, paeoniflorin suppressed HGF-mediated migration and invasion and actin cytoskeleton rearrangement of glioblastoma cells, and the mechanism involved c-Met/RhoA/ROCK1 signaling regulation." (PMID 30886866, 2019). "More important, we confirmed that NKCC1 accelerates EMT in glioblastoma cells via NKCC1‐dependent Rac1/RhoA activation." (PMID 30159893, 2019). "Stress fiber formation in glioblastoma cells in response to RhoA activation induced SPARC which was prevented by interrupting actin assembly with latrunculin A (Lat-A)." (PMID 31062076, 2019). "In our present research, HGF induced phosphorylation of c-Met and activates the RhoA/ROCK signaling in glioblastoma cells." (PMID 30886866, 2019). "Glioblastoma cells seem to exploit the structural flexibility of Nogo-A-Δ20 using SPARC as a soluble decoy to attenuate the activation of inhibitory RhoA signaling via S1PR2." (PMID 31062076, 2019). "StarD13 (START-GAP2) is a GTPase-activating protein (GAP) that specifically inhibits RhoA and Cdc42 in glioblastoma cells and other tumor models." (PMID 31698752, 2019). "We investigated the molecular mechanism by which glioblastoma cells produce SPARC in response to RhoA activation." (PMID 31062076, 2019). "Once translation is initiated, glioblastoma cells rapidly secrete SPARC to block Nogo-A from inhibiting migration via RhoA." (PMID 31062076, 2019). "In 2014, Sayyah's group published the first study showing that this small G-protein is required for glioblastoma cell growth in vitro by activating downstream signaling of G-protein-coupled receptor and RhoA utilizing Rap1 knockdown techniques." (PMID 31921670, 2019). "Syx controls the spatiotemporal regulation of mDia1 and ROCK activities through RhoA in migrating glioblastoma multiforme (U251) and mammary grand tumor (Hs578T) cells." (PMID 29659486, 2018). "Taken together, netrin-1 activates glioblastoma cell invasion in a RhoA-, CREB-, and CatB-dependent manner." (PMID 30532711, 2018). "Mechanistically, netrin-1 induces glioblastoma cell stress fiber formation by activating the RhoA and cofilin pathway." (PMID 30532711, 2018). "Consistent with the results of glioblastoma cells, netrin-1 induces EC stress fiber formation and invasion via a RhoA and cofilin pathway." (PMID 30532711, 2018). "Previous studies have shown that CD44 is redistributed to lamellipodia and subsequently cleaved and shed from the cell surface when RhoA is over-activated in human glioblastoma cells (U251MG)." (PMID 22363471, 2012). "Lastly, we demonstrate the pUS28-mediated activation of RhoA via Pyk2 also occurs in U373 glioblastoma cells." (PMID 21429240, 2010). "RhoA plays a significant role in the motility and invasion of glioblastoma cells." (PMID 41369326, 2025). "Moreover, STARD13, a GTPase-activating protein (GAP), inhibits RhoA and Cdc42 specifically in glioblastoma cells and other types of tumor models." (PMID 34952924, 2021). "RhoA is activated upon binding of glioblastoma cells to the extracellular matrix (ECM)." (PMID 32089990, 2020). "Similar effects could be observed also from Tseliou and colleagues, whereby a depletion of RhoA was discovered to result in significant alterations in the morphology of cultured glioblastoma cells." (PMID 33318498, 2020). "To determine whether paeoniflorin may regulate the Rho-GTPase in glioblastoma cells, we examined the RhoA activity." (PMID 30886866, 2019). "Glioblastomas strongly invade the brain by infiltrating into the white matter along myelinated nerve fiber tracts even though the myelin protein Nogo-A prevents cell migration by activating inhibitory RhoA signaling." (PMID 31062076, 2019). "Consequently, blocking Nogo-A-Δ20 with recombinant SPARC prevented RhoA activation in glioblastoma cells [Suppl." (PMID 31062076, 2019). "Furthermore, the inhibition of HGF-induced migration and invasion and actin cytoskeleton rearrangement involved c-Met-mediated RhoA/ROCK signaling in glioblastoma." (PMID 30886866, 2019).
glioblastoma (continued). "Since RhoA activation is a key event in inhibitory Nogo-A signaling, we expressed constitutively active RhoA (RhoAG14V) in glioblastoma cells to identify secreted matricellular proteins that may enable migration." (PMID 31062076, 2019). "Netrin-1 promotes glioblastoma and medulloblastoma cell invasion in a RhoA-dependent manner." (PMID 30532711, 2018). "Importantly, the effect of pUS28 activating Pyk2 is not cell-type specific as we observed comparable activation of Pyk2 and RhoA via pUS28 signaling in U373 glioblastoma cells." (PMID 21429240, 2010). "We have previously shown that the transmembrane protein ODZ1 serves for glioblastoma (GBM) cells to invade the surrounding tissue through activation of RhoA/ROCK pathway." (PMID 34376733, 2021). "Furthermore, the Nogo-A-Δ20 domain alone was enough to activate RhoA in glioblastoma cells [Suppl." (PMID 31062076, 2019). "Additionally, pUS28 activated RhoA via Pyk2 in the U373 glioblastoma cells." (PMID 21429240, 2010). "We have previously shown that the transmembrane protein ODZ1 promotes cytoskeletal remodeling of glioblastoma (GBM) cells and invasion of the surrounding parenchyma through the activation of a RhoA–ROCK pathway." (PMID 38727302, 2024). "Most importantly, the function of SOXC factors can be replaced by chemicals targeting RhoA, RAC1, CDC42, or their effectors, indicating a critical role of Rho GTPases played during neuronal reprogramming of human glioblastoma cells." (PMID 39390804, 2024). "We further establish that small molecules targeting RhoA and its effectors can substitute for SOXC factors in facilitating the neuronal reprogramming of glioblastoma cells." (PMID 39390804, 2024). "A study revealed that NKCC1/SLC12A2 was highly expressed in Glioblastomas and it promoted EMT-like process via RhoA and Rac1 signaling pathways." (PMID 38396064, 2024). "Thus, our study proved that paeoniflorin could inhibit migration and invasion and actin cytoskeleton rearrangement through inhibition of HGF/c-Met/RhoA/ROCK signaling in glioblastoma, suggesting that paeoniflorin might be a candidate compound to treat glioblastoma." (PMID 30886866, 2019). "Reduced IRE1α activity enables glioblastoma cells with activated AKT signaling to secrete SPARC, which prevents an intrinsically disordered region of Nogo-A-Δ20 from further inducing RhoA signaling via S1PR2." (PMID 31062076, 2019). "In contrast to our results MERTK knockdown in glioblastoma cells decreased migration but increased FAK and RhoA expression." (PMID 27081701, 2016). "Indeed, rhSFRP2 decreased RhoA activity induced by Wnt5A in both U251 and T98MG cells (glioblastoma)." (PMID 38802858, 2024). "In this context, TRPM8-mediated regulation of RhoA/ROCK might be responsible for the pro-tumoral effect of TRPM8, as the RhoA/ROCK pathway has been involved in the proliferation and migration of glioblastoma cells." (PMID 33240883, 2020). "TRPV1 has also been proposed as a negative prognosis marker for glioblastoma, in which invasiveness is highly dependent on RhoA activity since it regulates several matrix metalloproteinases in this type of neoplasms." (PMID 33240883, 2020). "EHT1864 blocks activation of Rac, but not the related proteins CDC42 or RhoA, at a concentration of 50 μM in glioblastoma cells." (PMID 28423521, 2017). "Furthermore, azathioprine’s actions as a guanine antagonist could be antiviral, as reported for Zika virus (ZIKV), where siRNA knockdown of RhoA and Cdc42 was shown to enhance ZIKV infection in glioblastoma cells." (PMID 38054722, 2024). "Moreover, we confirmed this RhoA-mediated induction of SPARC in previously reported patient-derived glioblastoma cells which were cultured in the absence of serum, thus excluding serum-derived effects [Suppl." (PMID 31062076, 2019).
glioblastoma (continued). "Therefore, while under normoxic conditions, EGF stimulates the activation of both the PI3K and the MAPK pathways and the induction of VEGF, in glioblastoma cells, hypoxic conditions lead to the suppression of the PI3K/RhoA/C pathway and an exclusive switch to the MAPK pathway." (PMID 31698752, 2019). "Glioblastoma cells have been shown to continuously produce high SPARC transcript levels; however, these levels do not correspond with the low SPARC protein level in cells without RhoA activation." (PMID 31062076, 2019).